Y_RNA (Y RNA )
Gene: Miscellaneous RNA gene on chromosome 4 (41,303,237 to 41,303,337, reverse strand). Ensembl gene ENSG00000207481.
Homologues: Orthologues: chimpanzee Y_RNA (100% identical), macaque Y_RNA (94% identical). Paralogues in human: RNY3 (92% identical), Y_RNA (92% identical), Y_RNA (91% identical), Y_RNA (90% identical), RNY3P1 (89% identical), Y_RNA (89% identical), RNY3P14 (88% identical), RNY3P16 (88% identical), Y_RNA (88% identical), Y_RNA (87% identical), RNY3P11 (86% identical), RNY3P2 (86% identical), and 96 more.